TFRC (transferrin receptor)
Diseases named in the same sentence as TFRC in open-access papers (continued):
Sharing a sentence is not in itself a finding about the gene and the disease.
tumor (continued). "Ferritin H-homopolymers have been extensively used as nanocarriers for different applications in the targeted delivery of drugs and imaging agents, due to their ability to bind the transferrin receptor (TfR1 or CD71), highly overexpressed in iron avid, fast replicating, tumor cells." (PMID 36770830, 2023). "Therefore, it can be used as a target receptor to recognize tumor cells, and transferrin receptor has been widely used in targeting strategies." (PMID 37919282, 2023). "TFRC depletion significantly decreased total tumor number and the tumor number at sizes of 2–3 mm." (PMID 36703617, 2023). "Although TFRC is an important iron uptake receptor in cancer cells, its functions and mechanisms in ferroptosis and tumor progression remain unclear." (PMID 37675227, 2023). "Furthermore, after down-regulating IGF2BP2, IHC staining of mouse tumor tissue sections with the TFRC antibody revealed that TFRC expression decreased after IGF2BP2 was down-regulated." (PMID 37088822, 2023). "Compared with normal tissues, the expression of TFRC is remarkably downregulated in tumor tissues." (PMID 37923740, 2023). "Tumor-induced extramedullary hematopoiesis produces abundant CD71 (transferrin receptor 1) positive EPCs suggesting that neutralizing CD71 could be an effective strategy to deplete these robust immunosuppressors." (PMID 37208766, 2023). "From a molecular mechanism perspective, this result also demonstrated that TFRC might promote tumor progression and is closely related to tumor immunity." (PMID 36483569, 2022). "Apoferritin, an unloaded natural iron protein with a cage-like structure and transferrin receptor 1 (TfR1) targeting ability, was loaded with melanin nanoparticles (AMF), 64Cu2+ and Fe3+ to image HT29, high TfR1 expression, and HepG2, low TfR1 expression, in tumor-bearing mice." (PMID 35159738, 2022). "Thus, its inactivation reduces transferrin receptor expression by suppressing cellular iron import and delaying tumor progression." (PMID 35456655, 2022). "Therefore, we carried out those primary analyses to clarify the relationship between TFRC and tumor immunotherapy." (PMID 36483569, 2022). "According to the CPTAC data, the protein expression of PKMYT1, ETF1, ECT2, BUB1B, and RECQL4 in tumor tissues was significantly increased, while the expression of TFRC was significantly reduced, and the expression of COCH and TUBB2B did not change significantly (PITX1 and CDC6 were not included)." (PMID 33869220, 2021). "In the HPA data, compared with normal tissues, the expression of PKMYT1, ETF1, RECQL4, TUBB2B, and CDC6 in tumor tissues was remarkably upregulated, while the expression of TFRC and PITX1 was significantly downregulated (,ECT2, BUBB1B, and COCH were not included)." (PMID 33869220, 2021). "To further determine whether TFRC-mediated tumor cell-imposed iron restriction promotes M2 polarization of macrophages, we examined the expression of M2 signature genes in BMDMs and PMs co-cultured with either Hepa1-6/shTfrc cells or their controls." (PMID 34389031, 2021). "To this end, we first examined TFRC levels in tumor tissues from Hepa1-6 tumor-bearing mice." (PMID 34389031, 2021). "TFRC has been reported to promote tumor migration via the positive regulation of AXIN2." (PMID 34151031, 2021). "Ferritin, an iron storage and transport protein, which could be specifically recognized by transferrin receptor 1 (TfR1) overexpressed cancer cells, has been investigated as a novel type of tumor-targeting platform." (PMID 34238297, 2021). "These modifications on TFRC mRNA have also influence tumor occurrence and proliferation." (PMID 34899345, 2021).
tumor (continued). "Moreover, the transferring receptor 1 protein (TFRC), involved in the homeostasis of intracellular free iron, a key factor triggering ferroptosis, was also up-regulated in tumor tissue." (PMID 33672863, 2021). "Furthermore, FRGs, IRGs, DEGs, and genes in the blue module were intersected, and seven hub genes (JUN, TNFAIP3, NOX4, HMOX1, SOCS1, CYBB, and TFRC), related to both ferroptosis and tumor immunity, were obtained." (PMID 35174170, 2021). "In addition, the transferrin receptor is highly expressed in various tumor cells, exhibiting the potential for targeted antitumor treatment." (PMID 32259795, 2020). "For instance, transferrin can be used as a targeting ligand for delivery into tumor cells through binding to the transferrin receptor, whose expression is enhanced in tumor cells to provide iron as a necessary cofactor for DNA synthesis and rapid cell proliferation." (PMID 32455572, 2020). "The concentration of iron atom in tumor cells is much higher than that of normal cells, which may be related to the high expression of transferrin receptor (TfR) on the surface of tumor cells." (PMID 32452511, 2020). "Anti-transferrin receptor antibody-ricin and transferrin-ricin immunotoxins have been tested in a variety of cancer settings where their cytotoxic activity was demonstrated to be highly potent, tumor cell type-specific and correlated with the expression of the transferrin receptor." (PMID 32957689, 2020). "HFn specifically binds to tumor cells which overexpress transferrin receptor 1 (TfR1) 9, 12-15, while the Fe3O4 core exerts peroxidase-like activity to catalyze the oxidation of substrate di-azo-aminobenzene (DAB) in the presence of H2O2 to give a color reaction." (PMID 31903145, 2020). "Recently, many reports found that TFRC is involved in tumor progression." (PMID 30782157, 2019). "Previously, EFNA1 and TFRC have been proposed as prognostic factors in CESC and were found to be sensible to natural compounds – it was shown, that (-)-epigallocatechingallate and curcumin treatment, similar to SM, significantly decrease expression of EFNA1 and TFRC in tumor cells, respectively." (PMID 31523389, 2019). "We believed macrophages from peritoneal lavage could up to some degree compete with tumor cells for the NDA135b since they are (in 7%) positive for transferrin receptor too." (PMID 31181619, 2019). "Because many malignant tumor cells express highly specific receptors such as human epidermal growth factor receptor 2 (HER2), transferrin receptor (TfR), and FA receptor (FR), albumin NPs can be chemically modified with the corresponding ligands to provide targeted tumor delivery." (PMID 31623082, 2019). "Immunohistochemistry (IHC) staining demonstrated transferrin receptor expression in the endothelium of tumor-associated blood vessels and on tumor cells in both U87MG and GL261 tumor-bearing mice, with relatively higher intensity of staining in U87MG compared to GL261 tumors (α-Tf Receptor)." (PMID 29777137, 2018). "Iron may also be critical for the action of artemisinin-type drugs towards tumor cells, because it is correlated with the expression of the transferrin receptor (CD71), which is responsible for cellular iron uptake." (PMID 29642419, 2018). "Interestingly, transferrin receptor, which can control iron metabolism, is frequently expressed in tumor cells." (PMID 28389657, 2017). "Xenograft model of breast cancer using eGFP-expressing mice showed that transferrin receptor is transferred from tumor cells to stromal cells in-vivo and this process is strongly correlated with an increased opposite transfer of eGFP from stromal to tumor cells." (PMID 28770210, 2017). "We hypothesized that FLI of bombesin and transferrin receptor expression can be used for early detection of treatment-induced tumor metabolic changes in a manner similar to the gold standard of 18F-FDG PET imaging." (PMID 28792505, 2017).
tumor (continued). "Furthermore, we have shown that this compound can be efficiently loaded into Tf-conjugated LPs for targeted delivery to tumor cells, which overexpress the transferrin receptor." (PMID 26309138, 2015). "As the tumour may be responsible for increased iron concentrations in the plasma, the transport may also be corrupted at the transferrin/transferrin receptor level." (PMID 25435931, 2015). "Transferrin receptors are increased in PDAC patient tumor tissues, and our analysis of the Badea dataset demonstrates TFRC up-regulation and down-regulation of ferritin in PDAC patients, recapitulating metabolic reprogramming by Ras which sensitizes transformed cells to ferroptosis." (PMID 26097885, 2015). "In fact, the iron transport protein transferrin (Tf) is crucial in tumor development since highly proliferative tumors have higher demand for iron than normal tissues, resulting in the overexpression of the transferrin receptor (CD71)." (PMID 25268716, 2014). "Moreover, we demonstrated that the anti-TFRC antibody efficiently inhibited tumor growth in a murine xenograft OSCC model." (PMID 24890018, 2014). "Expression of mRNA for Lcn2, Mmp9, Bdh2, 24p3R, megalin (another receptor mediating cellular uptake of lipocalin-2), and transferrin receptor (Tfrc) were determined in each tumor and reported as mean of all tumors/tissue samples in each of the four groups of mice." (PMID 22737251, 2012). "TFRC, transferrin receptor, is known to be expressed in many tumor types." (PMID 22761861, 2012). "Moreover, CLL and NHL have increasing expression of transferrin receptor correlating with the clinical stage of the tumour." (PMID 21504579, 2011). "Therefore, we speculated that TFRC may play an important role in regulating the biological functions of tumor cells by modulating iron uptake and affecting the activity of RRM2." (PMID 40510157, 2025). "TFRC has been confirmed to be highly expressed in a variety of malignant tumors and provides a sufficient iron source to support the rapid proliferation of tumor cells by promoting iron endocytosis, which is also considered an important promoting factor for tumor cell growth and poor prognosis." (PMID 40510157, 2025). "Moreover, the use of CRISPR/Cas9 technology to edit TFRC expression levels in cancer cells has shown potential in preclinical models, suggesting that manipulating TFRC could alter tumor growth dynamics and response to therapy." (PMID 40303995, 2025). "Moreover, TRRP could bind to the transferrin receptor on the surface of tumor cells, which enhanced the efficacy of TACE and reduced side effects of TACE." (PMID 38990300, 2024). "Furthermore, TFRC might be a potential biomarker for predicting the responses of tumours to anti‐PD‐1‐based therapies and the overall survival of HCC patients." (PMID 39095323, 2024). "Consequently, targeting TFRC presents a potential alternative strategy for tumor therapy." (PMID 39131609, 2024). "To mitigate the effects caused by loss of pyoverdine, we also employed the specific ferroptosis inhibitor, ferrostatin, which could also prevent ferroptosis of ΔpvdA mutant‐treated tumor spheroids, where lower levels of ROS and expression of transferrin receptor were observed." (PMID 39135304, 2024). "However, since we detected TFRC expression in the bone marrow and immune cells in the tumour microenvironment, TFRC-targeting might be less desirable compared to ablating NCBP2." (PMID 36635327, 2023). "Moreover, increasing the concentrations of TFRC-targeted superparamagnetic iron oxides in tumor tissues via magnetic fields could inhibit tumor progression, which is a promising cancer treatment." (PMID 37675227, 2023). "How IGF2BP2 regulates TFRC may be a watershed event in iron metabolism and tumor progression." (PMID 37088822, 2023). "Therefore, it may be useful to further investigate if TFRC regulates immune responses in the tumour microenvironment." (PMID 36635327, 2023).
tumor (continued). "Then, we investigated whether TFRC knockdown represses tumor formation in vivo." (PMID 37644594, 2023). "In addition, Peng Jiang developed TIDE (a computational method to model two primary mechanisms of tumor immune evasion), we found tumor associated macrophage M2 type and TIDE score were negatively correlated with TFRC, which further demonstrates the relationship between TFRC and immunotherapy." (PMID 35372510, 2022). "Thus, the results demonstrated that TFRC plays a certain role in influencing tumor progression." (PMID 36483569, 2022). "Besides, tumor mutation burden (TMB) has always been considered as one of the criteria for immunotherapy, so we analyzed the TMB and found that it was positively correlated with TFRC." (PMID 35372510, 2022). "Meanwhile, ferritin moieties could not only encapsulate β-lapachone (Lap) in the central cavity (Ft-Lap) at high yield through hydrophobic interaction, but also bind to transferrin receptor 1 (TfR1) overexpressed on tumor cell membrane to enable targeted Lap delivery." (PMID 36167857, 2022). "Therefore, high TFRC expression often leads to a relatively “hot” tumor microenvironment." (PMID 35372510, 2022). "The transferrin receptor 1 (TfR1) levels on the cell surface, which modulate the uptake of TF binding iron, are associated with cell proliferation rate and, not surprisingly, are increased in tumor cells, including CRC cells." (PMID 34829955, 2021). "Also, TFRC is shown to be positively related to tumor-infiltrating M2 macrophages." (PMID 34389031, 2021). "Moreover, Ru compounds can effectively bind to the serum transferrin receptor, which is highly expressed in tumor cells, thus increasing the number of Ru–transferrin complexes that could preferably be delivered at the tumor site." (PMID 34361543, 2021). "For example, the transferrin receptor (CD71) is generally expressed to regulate iron homeostasis within normal human cells, however, malignant tumours are often found to express abnormal levels of expression of the transferrin receptor (CD71), which may be targeted by antibodies in targeted PDT." (PMID 34830287, 2021). "However, the molecular mechanisms by which TFRC contributes to tumor progression remain elusive." (PMID 32867190, 2020). "Whereas iron accumulation in VHL-deficient ccRCC tumor cells might increase HIF-2α through IRP1 deactivation and in turn promote TFRC transcription, iron accumulation in VHL wild-type tissues would be expected to decrease HIF-2α through PHD activation and lead to TFRC downregulation." (PMID 29291011, 2017). "This nanoconstruct leverages HFn's natural affinity for transferrin receptor 1 (CD71) and scFv-mediated targeting of Claudin18.2 to achieve precise tumor localization." (PMID 41567734, 2026). "The expression levels of MMP1, TFRC, and CXCL8 were significantly upregulated in the tumor group compared to the normal group (p < 0.05)." (PMID 40809844, 2025). "The expression levels of TFRC, LAMC1, PLK1, TYMS, and TSSK6 were significantly higher in tumor tissues while TNFSF14 exhibited higher expression levels in normal tissues." (PMID 40496862, 2025). "For example, the transferrin receptor has been targeted by transferrin–drug conjugates and peptide-guided nanoparticles to ferry chemotherapeutics across the BBB and into tumor cells." (PMID 40918539, 2025). "TFRC and ALDH5A1 were located in the tumour, PDLIM3 in the stroma, and CA1 and APM2 in both regions." (PMID 40697100, 2025). "RT-qPCR analysis confirmed the significant upregulation of MMP1, TFRC and CXCL8 in tumor tissues, consistent with our previous differential gene-expression studies." (PMID 40809844, 2025). "Specifically, in the staining images of the tumour and stroma regions, ALDH5A1, TFRC, and PDLIM3 showed different staining intensities between the two regions, whereas APM2 exhibited poor recognition in differentiating tumour from stroma." (PMID 40697100, 2025).
tumor (continued). "An example is the bi-functional DNA aptamer TEPP that binds to both transferrin receptor (TfR) located on BBB endothelia cells and to the epithelial cell adhesion molecule (EpCAM) located on tumor cells within the brain." (PMID 40716251, 2025). "Our RT-qPCR results confirmed the upregulation of MMP1, TFRC, and CXCL8 in the tumor group, which was consistent with the findings of our previous analyses." (PMID 40809844, 2025). "Transferrin-SPIONs (Tf-SPIONs) bind transferrin receptors (TfR), while lactoferrin-SPIONs (Lf-SPIONs) engage lactoferrin receptors (LRP1), facilitating receptor-mediated endocytosis into tumor cells." (PMID 41583439, 2025). "Specifically, TFRC, PLK1, TYMS, and TSSK6 were remarkably upregulated in tumor tissues compared to normal controls (P < 0.0001)." (PMID 40496862, 2025). "The expression level of transferrin receptor 1 (TfR1) is significantly elevated in both the BBB and tumor cells compared to normal tissues." (PMID 40420216, 2025). "These HFn NPs naturally target the transferrin receptor 1 (TfR1), which is highly expressed on both the BBB and many tumor cells, enabling H-TZ to cross the BBB and specifically bind to HER2+ tumor cells." (PMID 40733107, 2025). "Activation of NFE2L2 in mouse xenograft tumour models also enhanced the expression of FTH1 and GPX4 and decreased the expression of TFRC to some extent." (PMID 38685674, 2024). "Ligand-receptor analysis between macrophages and tumor cells identify C5/C5AR1,SPP1/ITGA4, and TF/TFRC as the ligand-receptor signaling mechanism driving these niche-DE genes." (PMID 38217002, 2024). "With the exception of ASMTL, we observed upregulated mRNA levels of KIFC2, SMYD2, TFRC, and OPN3 in tumor tissues within these datasets." (PMID 39131609, 2024). "Among these tumour cells, the common LASS2 interaction partner transferrin receptor (TFRC) was analysed by protein–protein docking and validated by coimmunoprecipitation western blot, immunofluorescence, and proximity ligation assays." (PMID 38419028, 2024). "Collectively, these data strongly demonstrated that LASS2 requires TFRC as a direct target to induce GPX4-dependent ferroptosis and thus inhibit tumour metastasis." (PMID 38419028, 2024). "Most of these studies were performed in the context of tumours, and the regulatory mechanisms of ACSL4 and TFRC in other benign diseases still need to be investigated." (PMID 38834654, 2024). "In another recent study, they created dual-targeted NIS plasmid DNA complexes with targeting ligands for the EGFR and transferrin receptor (TfR), offering the possibility of active transport across the BBB and subsequent targeting of tumor cells." (PMID 39199662, 2024). "Transferrin receptor (TFRC) and fibronectin 1 (FN1), significant contributors at three months, contributed to the tumor regulation of viral production and multiple tumor cellular activities in cell line models." (PMID 39262965, 2024). "Xenograft mouse assay in vivo showcased tumor volume and weight in nude mice injected with SKOV3 cells; the weight and volumes were reduced after sh-circ-TFRC transfections." (PMID 38678242, 2024). "Together, our data reveal that TFRC depletion in colon epithelial cells can lead to decreased cellular iron levels, reduced POLD1 expression, increased apoptosis, and repressed tumor growth." (PMID 36703617, 2023). "We confirmed in vivo that TFRC knockdown also inhibited NPC tumor growth and decreased Ki67 expression in tumor tissues of nude mouse xenografts." (PMID 37644594, 2023). "Predictive models have indicated significant upregulation of TFRC expression in BLCA tissues, which correlates with clinical features and prognosis of the tumor." (PMID 38103068, 2023). "TFRC was significantly induced in the colons after Apc gene disruption and across CRC stages, indicating that tumor cells are dependent upon iron and have developed mechanisms to tolerate iron toxicity." (PMID 36703617, 2023).